IGKV3D-15 (immunoglobulin kappa variable 3D-15)
Description:
V region of the variable domain of immunoglobulin light chains that participates in the antigen recognition. Immunoglobulins, also known as antibodies, are membrane-bound or secreted glycoproteins produced by B lymphocytes. In the recognition phase of humoral immunity, the membrane-bound immunoglobulins serve as receptors which, upon binding of a specific antigen, trigger the clonal expansion and differentiation of B lymphocytes into immunoglobulins-secreting plasma cells. Secreted immunoglobulins mediate the effector phase of humoral immunity, which results in the elimination of bound antigens. The antigen binding site is formed by the variable domain of one heavy chain, together with that of its associated light chain. Thus, each immunoglobulin has two antigen binding sites with remarkable affinity for a particular antigen. The variable domains are assembled by a process called V-(D)-J rearrangement and can then be subjected to somatic hypermutations which, after exposure to antigen and selection, allow affinity maturation for a particular antigen.
Synonyms: IGKV3D15; L16; L16a; L16b; L16c
Gene: Immunoglobulin variable (V) gene on chromosome 2 (90,114,838 to 90,115,402, forward strand). Ensembl gene ENSG00000224041.
Subcellular location: Secreted; Cell membrane
Subcellular location (Human Protein Atlas): Cytosol; Plasma membrane; Predicted to be secreted
Gene Ontology:
Biological process: immune response
Cellular component: extracellular region; immunoglobulin complex; plasma membrane
Homologues: Orthologues: mouse Igkv18-36 (65% identical), rat Igkvl13 (63% identical). Paralogues in human: IGKV3-15 (98% identical), IGKV3OR2-268 (91% identical), IGKV3-11 (90% identical), IGKV3D-11 (89% identical), IGKV3-20 (88% identical), IGKV3-7 (88% identical), IGKV3D-20 (86% identical), IGKV3D-7 (86% identical), IGKV1-5 (71% identical), IGKV1D-8 (70% identical), IGKV1-8 (70% identical), IGKV1-9 (70% identical), and 81 more.